ANGPT2 (angiopoietin 2)
Diseases named in the same sentence as ANGPT2 in open-access papers (continued):
Sharing a sentence is not in itself a finding about the gene and the disease.
tumor (continued). "Next, to dissect the mechanism of how ERβ can increase the HUVEC tube formation, we focused on tumor angiogenesis-related genes, including Angiogenin, ANGPT-2, bFGF, EGF, HB-EGF, HGF, Leptin, PLGF, and VEGF-A35." (PMID 32409702, 2020). "Angiopoietin-2 levels also corelated with tumour load and survival in patients with cutaneous malignant melanoma." (PMID 33082849, 2020). "ANGPT2 has been found to be highly expressed in diverse tumor cells and plays an important role in tumor angiogenesis and inflammation." (PMID 32183816, 2020). "Tumor biopsies with high tumor vascular ANGPT2 expression showed an increase in CD68+ and CD163+ macrophages after Ipilimumab or Ipi-bev treatment." (PMID 32793228, 2020). "Since the Angiopoietin-2 (Ang2)/Tyrosine-protein kinase receptor-2 (Tie2) kinase signaling pathway is pivotal in tumor angiogenesis 18, we investigated the influence of naringenin treatment on this pathway." (PMID 33173425, 2020). "Next, Angpt2 genotypes in patients with CRC were investigated to clarify the risk of Angpt2 polymorphisms as according to clinical TNM stage, tumor site and pathologic grade." (PMID 31929743, 2020). "Eventually, 3 potential target genes of miR-145-5p were achieved, among which ANGPT2 was significantly up-regulated in tumor samples." (PMID 32874130, 2020). "The expression of angiopoietin-2 is upregulated at sites of tumor angiogenesis in multiple types of cancer, and overexpression of angiopoietin-2 promoted angiogenesis and tumor growth in experimental models." (PMID 32799882, 2020). "When Tie-2 on the surface of TEMs binds to angiopoietin-2 secreted from endothelial and tumor cells, a strong angiogenic switch is turned on in the TME." (PMID 32913278, 2020). "Angiopoietin-2, a molecule responsible for angiogenesis and cancer progression which corelates with tumour load in certain cancers, is upregulated by angiotensin 2-AT1 Receptor axis." (PMID 33082849, 2020). "Taken together, these results reveal a novel pathway of tumor angiogenesis induced by HCC cell-secreted exosomal ANGPT2 that is different from the classic ANGPT2/Tie2 pathway." (PMID 32183816, 2020). "ANGPT2, a factor suppressed by VEGFs, has been studied on its activity in clinical tumor models, and its up-regulation has been considered as one of the mechanisms of acquired drug-resistance during anti-VEGFs treatment." (PMID 32874130, 2020). "Preclinical studies have demonstrated beneficial effects on inhibiting tumor progression by dual inhibition of ANGPT-2/VEGFR2." (PMID 31690961, 2020). "Co-targeting of ANGPT-2/VEGFR2 is also effective in other murine tumor models, including early breast cancer, colorectal and renal cancer." (PMID 31690961, 2020). "The overexpression of SPP1 and ANGPT2 in EC tissue samples also indirectly confirmed that abnormal tumor angiogenesis was closely related to the occurrence of EC by activating the tumor angiogenesis." (PMID 32908897, 2020). "A low expression of angiopoietin-2 was also significantly related to high grade tumors, size of residual tumor after primary surgery and the recurrence of cancer (p = 0.008; p = 0.012; p = 0.018) in the whole study population." (PMID 33151982, 2020). "ANGPT2 is an essential factor for the formation of vessels that encapsulate tumor clusters (VETC), which is a unique vascular pattern that is associated with HCC progression." (PMID 32644941, 2020). "While ANGPT1 stabilizes the tumor vasculature through recruitment of pericytes to growing vessels, ANGPT2 strongly promotes excessive angiogenic sprouting with reduced pericyte coverage." (PMID 32913278, 2020). "Expression levels of ANGPT1 and ANGPT2, were measured in tumor TCM following treatment with 1,4-dihydroxy quininib alone or in combination with Bevacizumab or FOLFOX." (PMID 33008336, 2020). "In the samples analyzed by the MELC technique, VEGFR‐3 was mainly detected in the tumor vasculature, while ANGPT2 was highly expressed by the tumor cells." (PMID 31069961, 2019).
tumor (continued). "Except for tumor cells, endothelial cells automatically produce angiopoietin 2 (Ang2), which interacts with integrin β1 and results in reduced barrier function, leading to enhanced transendothelial migration." (PMID 31835465, 2019). "When examining cytokines, within the group of BAP1-expressing tumours, 8q gain was related to an increased expression of ANGPT2 (p = 0.040) and a decreased expression of VEGF-B (p = 0.022) and VEGF-C (p = 0.026)." (PMID 31337000, 2019). "For example, anti-PD1 treatment combined with anti–angiopoietin-2 or anti-CSF1 antibodies suppresses tumor development in several mouse models." (PMID 31249132, 2019). "The model included simulations of M1 release of nitric oxide, M2 release of general tumor growth factors, TEM secretion of angiopoietin-2 and IL-10, and evaluated their effects on tumor progression." (PMID 31075118, 2019). "ANGPT2 is a secreted growth factor that sensitizes endothelial cells to different proangiogenic factors, such as VEGFs, and it has been shown to promote tumor metastasis, angiogenesis, and lymphangiogenesis." (PMID 31069961, 2019). "For example, miR-524 suppresses angiogenesis and tumor growth by functionally inhibiting the translation of angiopoietin-2." (PMID 32082362, 2019). "ANGPT2 has been shown to be highly expressed in tumors, promoting endothelial disruption and facilitating tumor cell extravasation." (PMID 31069961, 2019). "As tumor tissue expresses high amounts of angiopoietins during vasculogenesis (mainly ANGPT2), in OC patients, preoperative systemic levels are altered per se and correlate with their oncologic prognosis." (PMID 31396019, 2019). "During surgical treatment of peritoneal carcinomatosis, ANGPT2 is released into systemic circulation by mechanical trauma of vascular endothelial and tumor cells." (PMID 31396019, 2019). "In a following study, it was also elucidated that Angiopoietin-2 (Ang-2), another Tie2 ligand upregulated in tumor hypoxia, can also recruit TEMs." (PMID 31474975, 2019). "While VEGFR‐3 was mainly detected in the tumor vasculature, ANGPT2 was highly expressed by the tumor cells." (PMID 31069961, 2019). "Angiopoietin-2 (Ang-2, ANGPT2) is another important factor that cooperates with VEGF to drive tumor angiogenesis." (PMID 31394786, 2019). "Dual VEGF-A and ANGPT2 blockade also leads to substantial tumor inhibition and significantly extends the survival of transgenic MMTV-PyMT mice." (PMID 29766399, 2018). "In the process of angiogenesis, CTGF has been demonstrated to be the regulator of ANGPT2 expression, which is key factor for tumor angiogenesis." (PMID 29977158, 2018). "Among the other upregulated factors such as EGF, vascular endothelial growth factor (VEGF), angiopoietin-2 (Ang-2), and basic fibroblast growth factor (bFGF), are all well-known for their tumor promoting or EMT-inducing effects, except endostatin." (PMID 29329547, 2018). "These include: (i) angiopoietin-2 (Ang-2) receptor, Tie2, expressing monocytes (TEM), (ii) myeloid-derived suppressor cells (MDSC), (iii) tumor-associated neutrophils (TAN), and (iv) tumor- associated dendritic cells (TADC)." (PMID 30619287, 2018). "Vascular endothelial growth factor (VEGF) and Angiopoietin-2 (Ang-2), both essential in tumor angiogenesis and escape, are being studied in various combination bispecific formats [NCT03035253], [NCT03292783], [NCT02665416], NCT03030287] (No Title." (PMID 30249178, 2018). "Tie2+ TAMs are closely associated with tumor vasculature and have been found crucial for angiogenesis in orthotopic and transgenic tumor models, which depend on endothelial cell-produced angiopoietin-2 (ANG2) and Tie2 receptors on TAMs along the vasculature." (PMID 28241846, 2017). "Blocking of ANGPT2 protein or genetic deletion of TIE1 has been shown to decrease tumor angiogenesis and growth by reducing endothelial cell sprouting and by inducing endothelial cell apoptosis and vessel regression." (PMID 29017512, 2017).
tumor (continued). "To better understand the tumor-suppressive effect of miR-145 in breast tumorigenesis, we used online databases to predict the targets of miR-145 and confirmed that ANGPT2 was the direct target of miR-145." (PMID 28977900, 2017). "Holash and colleagues reported that both VEGF and Angiopoietin-2, or perhaps the equilibrium between the two, influence tumor growth and vascular regression, prompting us to measure the effects of MMPI on Angiopoietin-2." (PMID 28633655, 2017). "ANGPT2 is a member of the angiopoietin family, which contributes to tumor development and progression by linking the metastatic inflammasome with the angiogenic program." (PMID 28977900, 2017). "They mediate tumor development and metastasis by regulating the expression of genes involved in angiogenesis, such as Vegfa, Cyr61, and Angpt2, and thus remodeling cell survival and ECM." (PMID 28212608, 2017). "It is known that Angpt2 is elevated in many human cancers and preclinical studies of anti-Angpt2 agents often demonstrate additive anti-angiogenic effects on primary tumor growth when combined with inhibitors of the VEGF pathway." (PMID 28800750, 2017). "It is evident that more studies are needed to define how Angpt1, Angpt2 and Tek act in tumor growth and what their roles are in metastasis in order to develop better therapies." (PMID 28800750, 2017). "To determine the extent to which ANGPT2 contributes miR-145’s tumor suppression functions, we ectopically expressed an ANGPT2 construct together with miR-145 in MDA-MB-231 cells." (PMID 28977900, 2017). "Of note, ANGPT2, generally thought to be only expressed in ECs, was also up-regulated in tumour cells." (PMID 27049916, 2016). "Following estrogen depletion, the BM niche cells produced angiopoietin-2 (ANGPT2), which destabilized niche endothelium by interfering ANGPT1/Tie2 signaling, and promoted ER+ tumor cell survival under estrogen deficiency via cell surface integrin &1." (PMID 27353038, 2016). "This phenomenon is called 'angiogenic switch' and is characterized by the upregulation of pro-angiogenic molecules like vascular endothelial growth factor (VEGF) or angiopoietin 2 (Ang-2) that induce fast tumor angiogenesis." (PMID 26830460, 2016). "A number of known tumour associated angiogenic genes were identified by this analysis, including interleukin 8, angiopoietin 2 and lysyl oxidase like 2, validating the approach as a method for identifying genes enriched on tumour endothelium." (PMID 26943033, 2016). "Angiopoietin-2 ameliorated the dormancy of ER+ tumor cells in BM endothelial niche and promoted their survival under estrogen deficiency via integrin &1 (ITGB1)." (PMID 27353038, 2016). "Then, the patients were further stratified into two groups based on angiopoietin-2 mRNA (ANGPT2) levels in tumor tissue." (PMID 27353038, 2016). "The Angiopoietin-2 (Ang2, Angpt2) growth factor is a context-dependent antagonist/agonist ligand of the endothelial Tie2 receptor tyrosine kinase and known to promote tumour angiogenesis and metastasis." (PMID 27100185, 2016). "Angiopoietin 2 (Ang2) is a growth factor expressed in a variety of tumor types, which correlates with increased angiogenesis and poor prognosis." (PMID 26442214, 2015). "In contrast, in poorly differentiated tumours a higher gene expression of VEGF, EFNB2 and ANGPT2 was observed in tumours with lymphatic spread." (PMID 26044849, 2015). "Elevated preoperative levels of ANGPT2 and TuM2PK significantly correlated with increased tumor size and advanced grade (p < 0.05)." (PMID 25885592, 2015). "The synergistic effect of VEGF and ANGPT2 then obviously results in tumour angiogenesis and poor prognosis." (PMID 26044849, 2015). "A distinctive expression profile of VEGFA, EFNB2, PECAM1/CD31, ANGPT1 and ANGPT2 was revealed: VEGFA, EFNB2, and ANGPT2 were found overexpressed in 84 % to 95 % of tumour samples." (PMID 26044849, 2015).
tumor (continued). "In the presented data, a low ANGPT1/ ANGPT2 expression ratio was observed especially on gene expression level in patients which were diagnosed with a larger tumour size." (PMID 26044849, 2015). "Another striking result elucidated by our analysis of OSCC tumours is the oppositional regulation of ANGPT1and ANGPT2." (PMID 26044849, 2015). "We found that in the tumor tissue Follistatin and Angiopoietin-2 are differentially expressed between the two tumor types with significantly higher median tissue levels of the two angiogenic factors in SCC patients when compared to AEG patients." (PMID 25885021, 2015). "Among NFAT downstream effectors that are involved in the development and maintenance of tumor microenvironment, ANGPT2 has been shown to promote tumor growth and angiogenesis." (PMID 25811856, 2015). "The overexpression of angiopoietin-2 and VEGF in TC progression and a strong association between tumor size and high levels of VEGF and angiopoietin-2 were evidenced." (PMID 26635725, 2015). "The activation of STAT3 results in expression of many target genes including matrix metalloproteinases (MMPs), cyclooxygenase-2 (COX-2) and angiopoietin-2 (Ang-2) which are required for tumor cell migration, angiogenesis as well as metastasis." (PMID 26575424, 2015). "Expression of angiopoietin-2 by tumor cells induces the recruitment of Tie-2-expressing monocytes in the tumor and the release of IL-10 by the cells." (PMID 24765614, 2014). "The anti-angiogenic (CXCL9, CXCL10) and pro-angiogenic markers (VEGFa, CXCL2, CXCL5, Angiopoietin 1 and Angiopoietin 2) were quantified in the tumor by RTQPCR." (PMID 22815789, 2012). "Angiopoietin-2 levels were higher when tumour necrosis was present (P=0.01), but necrosis data was missing in 48% of cases." (PMID 21081932, 2011). "In comparison, angiopoietin-2 (ANGPT2) is expressed in the endothelium, tumor cells, macrophages and muscle cells." (PMID 21829546, 2011). "In fact, they found a strong association between tumor size and high levels of VEGF and angiopoietin-2." (PMID 29147212, 2010). "Three genes, DEFA1, DEFA3 and LOC728358, map to a refined region in 8p23.1 (8:6789275-6889920) and the ANGPT2 gene maps an adjacent region (8:6342789-6444367) and all show decreases expression in the tumor samples." (PMID 20799942, 2010). "NOS3, VEGFR-2, and ANGPT2 levels correlated inversely with tumor reduction after chemotherapy." (PMID 41749831, 2026). "In conclusion, gene set enrichment analysis revealed a connection between ANGPT2 and the immune system, with ANGPT2 level showing a strong positive correlation with tumor microenvironment cell infiltration, immune cell markers, and immune checkpoint expression." (PMID 41823527, 2026). "Beyond single anti-angiogenic therapy, the combination of VEGFA neutralization and angiopoietin 2 (ANGPT2) inhibition has been shown to normalize tumor vasculature, which can improve drug delivery, increase sensitivity to radiation therapy, and enhance immune cell infiltration in TME." (PMID 39849659, 2025). "The downregulation of these VEGFs following the cessation of PEMF therapy may suppress angiopoietin-2-induced vascular sprouting and tumor growth as previously reported." (PMID 40072060, 2025). "Tie‐2 on the surface of the TME promotes tumour angiogenesis by binding with ANGPT2." (PMID 40268524, 2025). "Damaged LSECs release vascular endothelial growth factor (VEGF) and angiopoietin-2 (ANGPT2), increasing vascular permeability and providing a physical pathway for circulating tumor cells (CTCs) to extravasate, thereby promoting intrahepatic metastasis and early recurrence." (PMID 40458724, 2025). "Additionally, the inhibition of ANGPT2 further restrains the malignant progression of tumor blood vessels." (PMID 40370455, 2025).
tumor (continued). "Aqueous extract of Agrostemma githago seeds showed the ability to inhibit angiogenesis, which was associated with changes in the release of VEGF, MMP2/9, and ANG2 (angiopoietin-2; crucial in vascular remodelling and tumour angiogenesis) from cancer and endothelial cell lines." (PMID 40725141, 2025). "In addition, in the TCGA database, both MAGEA3 and ANGPT2 were found to be significantly overexpressed in tumor tissues compared to normal tissues." (PMID 40342736, 2025). "Notably, we identify ANGPT2, PCSK1N, and GPX3 as key subtype-specific biomarkers, with ANGPT2 driving tumor progression in C1 and emerging as a potential therapeutic target." (PMID 41400463, 2025). "Another mechanism of tumor resistance involves the upregulation of angiopoietin-2 (Ang-2)." (PMID 40872551, 2025). "Angiopoietins, especially ANGPT-2, play a role in shaping the tumor vasculature." (PMID 40872551, 2025). "This suggests that ANGPT2 may not only serve as a specific biomarker for subtype C1 but also act as a regulator of tumor progression and the tumor’s ability to adapt to hypoxic conditions." (PMID 41400463, 2025). "Elevated levels of ANGPT2 could lead to a more aggressive tumor phenotype and poorer prognosis by promoting vascular permeability and destabilization, thereby facilitating tumor cell dissemination." (PMID 40061897, 2025). "However, there was significantly robust expression of ANGPT2 in tumor vessels in the refractory Bev group (24.36/5 HPF) compared with that in the naïve (8.68/5 HPF) and effective (9.60/5 HPF) Bev groups." (PMID 38619734, 2024). "Moreover, CAF2 was predicted to interact with tumor endothelial cells (TECs) including tip cell and venous TECs via the ANGPT2-(ITGA5 + ITGB1) and PGF-VEGFR1 axes, suggesting a role in promoting endothelial cell proliferation and migration." (PMID 39093451, 2024). "The Angiopoietin 2 (ANG2), having a role in hepatocyte proliferation, and the ST14 Transmembrane Serine Protease Matriptase (ST14), whose inhibition was associated with tumour cell invasion and metastasis, were also down-regulated." (PMID 38528259, 2024). "Moreover, angiopoietin-2, FAP and VEGF-A significantly (p < 0.05–0.001) associated with tumor grade, size, myometrial invasion, and mismatch repair status." (PMID 39511039, 2024). "Additionally, it plays a significant role in tumor progression and chemotherapy resistance by regulating a variety of angiogenic factors, including angiopoietin 1 and angiopoietin 2, matrix metalloproteinase, and erythropoietin, along with energy pathways." (PMID 38542288, 2024). "Moreover, tip tumor-associated ECs express genes associated with EC migration, matrix remodeling and VEGF signaling such as CXCR4, PDGF, and ANGPT2, whereas stalk ECs upregulate genes involved in vessel maturation and integrity as well as DII4-Notch signaling." (PMID 38426109, 2024). "Our previous and present data indicate that ANGPT1 and ANGPT2 might be reciprocally regulated during tumor oxygenation but upregulated together in the refractory period." (PMID 38619734, 2024). "The significance of VEGF, EPO, and angiopoietin-2 in tumor nutrition and metastasis is well documented, suggesting that ALA may exert a limiting effect on tumor growth and metastasis." (PMID 39199143, 2024). "The angiopoietin-2 (ANG2)-TIE2 axis is also a crucial mechanism for tumour angiogenesis." (PMID 38303024, 2024). "Angiopoietin-2 (ANGPT2) plays a significant role in promoting tumor angiogenesis and inflammation." (PMID 39227992, 2024). "Angiopoietin-2 (ANGPT2) as a key factor of angiogenesis drives tumor progression." (PMID 36907878, 2023). "Additionally, we observed an elevated level of ANGPT2 in human PanNET primary tumor samples as compared with healthy pancreatic samples in the RNA-Seq data set." (PMID 37843277, 2023). "High expression of ANGPT2 promotes tumor angiogenesis, growth, invasion and metastasis." (PMID 36907878, 2023).